RHOA (ras homolog family member A)
Diseases named in the same sentence as RHOA in open-access papers (continued):
Sharing a sentence is not in itself a finding about the gene and the disease.
ovarian carcinoma (continued). "In this study, we first demonstrated the interactions between FPR2 and RhoA in epithelial ovarian cancer cells." (PMID 34930387, 2021). "In this study, we preliminarily clarified the positive correlation of FPR2 and RhoA in ovarian cancer cells, and a RhoA inhibitor reversed the migration ability of EOCs, which was promoted by ectopic expression of FPR2." (PMID 34930387, 2021). "To further prove the role of arginine deprivation in the decrease in activation of RhoA, we depleted RhoA from SKOV3 ovarian cancer cells." (PMID 33423701, 2021). "It activates integrin-mediated FAK and RhoA to sensitize ovarian cancer cells to paclitaxel in the extracellular matrix." (PMID 33987033, 2021). "Increased ROR1 expression resulted in elevated RhoA, YAP/TAZ, and BMI-1 levels in a panel of OC cell lines as well as primary ovarian cancer patient-derived cells, underlining the translational relevance of our studies." (PMID 32989221, 2020). "Simvastatin has been recently reported to target cellular plasticity and retard ovarian cancer metastasis as well as stemness by the downregulation of the Hippo/YAP/RhoA pathway." (PMID 33207810, 2020). "Other authors have shown that knockdown of RBP4 significantly reduces ovarian cancer cell migration and proliferation driven through the RhoA/Rock1 and extracellular signal-regulated kinase (ERK) pathways." (PMID 32156052, 2020). "There is a link between Ran and RhoA signaling that contributes to enhanced ovarian cancer cell growth and invasiveness." (PMID 32512900, 2020). "The correlation of SMURF1 overexpression and RhoA/ROCK signaling pathways promoting metastasis was observed in ovarian cancer cell lines (OVCAR3)." (PMID 32443784, 2020). "Here, the authors show that Ran binds RhoA to impair its degradation and allow its localisation to the plasma membrane of ovarian cancer cells for tumour invasion." (PMID 31209254, 2019). "The rs927062 variant of ARHGAP5 was found to be associated with increased endometrioid and invasive serious ovarian cancer risk and a statistically significant decrease of ARHGAP5 protein which would be predicted to increase Rac1 and RhoA activity." (PMID 31344967, 2019). "The tumorigenesis and progression of ovarian carcinoma were regulated through RhoA Pathway, the inhibition of RhoA inhibited ovarian cancer cell proliferation, metastasis and invasion." (PMID 30795761, 2019). "The fact that ovarian cancer cell proliferation and invasion can be affected by disrupting the interaction between Ran and RhoA provides a rationale to develop advanced pharmacological compounds to prevent ovarian cancer cell progression." (PMID 31209254, 2019). "In summary, this study provides an undescribed link between Ran and RhoA signaling that collectively contributes to enhanced ovarian cancer cell growth and invasiveness." (PMID 31209254, 2019). "We demonstrate here that downregulation of Ran affects ovarian cancer cell proliferation and invasion through a proteasome-mediated degradation of RhoA which leads to PM restricted RhoA activity." (PMID 31209254, 2019). "As for ovarian cancer chemotaxis, RhoA and Rac1 were suggested to play independent roles in the chemotactic migration of ovarian cancer cells, inhibition of RhoA and Rac1 decreased cancer cell migration in LPA-induced chemotaxis." (PMID 30795761, 2019). "Accordingly, targeting of RhoA signalling by the HMG-CoA reductase inhibitor Lovastatin re-sensitized chemo-resistant ovarian cancer cell lines to doxorubicin in vitro." (PMID 30909510, 2019). "Our results indicated that RBP4 can drive ovarian cancer cell migration and proliferation via RhoA/Rock1 and ERK pathway." (PMID 29642915, 2018). "In fact, blocking or silencing of CXCR4 was found to significantly reduce RhoA and Rac-1/Cdc42 expression levels and decrease ovarian cancer cell migration." (PMID 30261690, 2018).
ovarian carcinoma (continued). "Another study demonstrated that treatment that suppressed RhoA signaling reduced the migration and invasive activity of human ovarian cancer cells." (PMID 28767067, 2017). "Treating ovarian cancer cells with statins and inhibitors of RhoA resulted in decreased cell dissemination in a NUDE mouse model of ovarian cancer." (PMID 27329838, 2016). "Evaluation of Gα13-specific signalingpathways in SKOV3 or HeyA8 ovarian cancer cell lines indicate that Ric-8Apotentiates Gα13-mediated activation of RhoA, Cdc42, and thedownstream p38MAPK." (PMID 27096001, 2015). "RhoA and Wnt-5a mRNA and protein expression were quantified in normal fallopian tube epithelium, benign cystadenoma (serous and mucinous), primary ovarian carcinomas, and metastatic omentum using real-time polymerase chain reaction (PCR) and western blotting." (PMID 24351810, 2013). "RhoA and Wnt-5a mRNA and protein expression in normal fallopian tube epithelium, benign tumors, primary ovarian carcinomas, and metastatic omentum were quantified." (PMID 24351810, 2013). "RhoA or Wnt-5a was knocked down in OVCAR3 ovarian carcinoma cells using siRNAs and cell phenotype and expression of relevant molecules were assayed." (PMID 24351810, 2013). "To study the molecular mechanisms, we observed the effects of RhoA or Wnt-5a knockdown on the phenotypes and expression of molecules regulated in ovarian carcinoma cells in vitro." (PMID 24351810, 2013). "RhoA has potential as a biomarker of tumorigenesis, differentiation, and progression in ovarian carcinoma." (PMID 24351810, 2013). "RhoA mRNA expression was positively correlated with that of Wnt-5a mRNA in ovarian carcinoma tissue." (PMID 24351810, 2013). "RhoA mRNA expression was significantly positively correlated with Wnt-5a mRNA expression in ovarian carcinoma (p = 0.001, R2 = 0.1669)." (PMID 24351810, 2013). "RhoA and Wnt-5a expression were positively correlated in ovarian carcinoma (p = 0.001, R2 = 0.1669)." (PMID 24351810, 2013). "This article reviews the roles of ECT2 and RhoA/ROCK signaling pathways in ovarian cancer, cervical cancer, and endometrial cancer, and summarizes and discusses the research progress of downstream molecules, transduction pathways, and mechanisms related to them." (PMID 40655948, 2025). "These suggest that the Ran-RhoA signaling complex may be a molecular target to control ovarian cancer metastasis and may be a potential therapeutic pathway." (PMID 40655948, 2025). "This special localization of RhoA is critical to ovarian cancer cell proliferation and invasion." (PMID 39510185, 2024). "In breast and ovarian cancers, physical interactions of CD44v3 with the extracellular matrix component hyaluronic acid and the cytoskeletal protein Ankyrin induce tumour cell migration through the stimulation of Rac1 and RhoA Rho GTPases." (PMID 36528833, 2023). "A study suggested that RhoA/ROCK may be related to cyclin D1 levels in ovarian cancer, and our results also indicate that the level of RhoA may be affiliated with cyclin D1." (PMID 35725908, 2022). "Finally, the data show that RhoA is required for matrix degradation and invasion of ovarian cancer cells independently from StarD13." (PMID 34958986, 2022). "Furthermore, RhoA is required for lysophosphatidic acid (LPA)-induced YAP dephosphorylation in ovarian cancer cells for long-term migration." (PMID 36369000, 2022). "PCGEM1 overexpression might cause carcinogenesis in ovarian cancer and affect its development by modulating YAP, P70S6K, RhoA, Bcl-xL and MMP2 protein levels." (PMID 35109849, 2022). "Here, we investigated whether RhoA is involved in the role of FPR2 in ovarian cancer invasion and migration." (PMID 34930387, 2021). "Thus, we suggest that FPR2 stimulates M2 macrophage polarization and promotes invasion and metastasis of ovarian cancer cells through RhoA." (PMID 34930387, 2021).
ovarian carcinoma (continued). "Moreover, this works highlights the similarity between RhoA depletion and arginine deprivation in terms of regulation of the migration and the adhesion dynamics of ovarian cancer cells." (PMID 33423701, 2021). "Therefore, we suggest that FPR2 stimulates M2 macrophage polarization and promotes invasion and metastasis of ovarian cancer cells through RhoA." (PMID 34930387, 2021). "The results confirm that autophagy reduces ovarian cancer cells motility by inhibiting RhoA." (PMID 33423701, 2021). "Authors in this study demonstrated a link between Ran and RhoA signaling pathway and suggested that downregulation of Ran might affect ovarian cancer cell proliferation through a degradation of RhoA by shifting its balance." (PMID 32443784, 2020). "Similarly, pre-treatment with an inhibitor of RhoA (C3) and Y-27632 led to the decrease in leptin-induced expression of urokinase plasminogen activator and inhibited the invasiveness of ovarian cancer (OVCAR3, SKOV-3, CAOV-3) cells." (PMID 32443784, 2020). "Moreover, the knockdown of Ran leads to a reduction of ovarian cancer cell invasion by impairing RhoA signalling." (PMID 31209254, 2019). "Our findings describe a signaling pathway involving Ran that regulates EOC invasion through RhoA GTPase activity and may lead to alternative therapeutic strategies for ovarian cancer." (PMID 31209254, 2019). "Moreover, RhoA overexpression increases ovarian cancer cell invasiveness in vitro, and nude mice implanted with RhoA overexpressing cells developed a significantly greater number of disseminated tumours." (PMID 30909510, 2019). "Since RhoA and Rac1 are often reciprocally active, connections between the two GTPases may need further analysis in ovarian cancer." (PMID 30261690, 2018). "To assess whether RhoA might also be involved in the platelet-induced dephosphorylation of YAP1 in detached ovarian cancer cells, we performed RhoA pulldown activation assays in HEYA8 and OVCAR8 cells." (PMID 28827520, 2017). "We investigated the roles of RhoA and Wnt-5a in ovarian carcinoma." (PMID 24351810, 2013). "In the present study, we found that tumor-derived ADM could polarize macrophages similar to TAMs, and then polarized macrophages promote the migration of ovarian cancer cells via activation of RhoA signaling pathway in vitro." (PMID 23434647, 2013). "RhoA is a potential tumorigenesis, differentiation, and progression biomarker in ovarian carcinoma." (PMID 24351810, 2013). "In conclusion, ADM could polarize macrophages similar to TAMs, and then polarized macrophages promote the migration of ovarian cancer cells via activation of RhoA signaling pathway in vitro." (PMID 23434647, 2013). "For example, the MEK/ERK signaling pathway, which was reported to be constitutively activated in epithelial ovarian cancer cells, has been shown to restore stress fibers in transformed fibroblasts, and a recent study suggested that Plexin-B1 can utilize RhoA to stimulate ERK." (PMID 21059203, 2010). "Additionally statin induced suppression of RhoA has been shown to inhibit peritoneal dissemination of ovarian cancer cells in vivo." (PMID 20359358, 2010). "However, RhoA expression was upregulated in metastatic omentum compared to ovarian carcinomas; additionally, RhoA expression was positively associated with FIGO stage and degree of differentiation in ovarian carcinoma." (PMID 24351810, 2013). "In conclusion, we have demonstrated that MCAM have multiple effects on epithelial ovarian cancer cell properties, including invasion, apoptosis and spreading on extracellular matrix, which may be related to the dysregulation of small Rho GTPase (RhoA and Cdc42)." (PMID 22610942, 2012). "And through the correlation analysis of the expressions of ECT2 and RHOA, ROCK1, and ROCK2 in ovarian cancer samples in TCGA database, it was found that the expression of ECT2 was significantly positively correlated with RhoA, ROCK1, and ROCK2." (PMID 40655948, 2025).
ovarian carcinoma (continued). "In ovarian cancer (OC), circ-NOLC1 binds to ESRP1 and upregulates CDK1 and RhoA expression to promote OC progression." (PMID 40864495, 2025). "In ovarian cancer, TAGLN senses changes in environmental stiffness and mediates ovarian cancer progression by regulating the RhoA/ROCK pathway." (PMID 39781462, 2025). "We demonstrated that circ-NOLC1 promotes ovarian cancer tumorigenesis and development by binding to ESRP1 and modulating CDK1 and RhoA levels." (PMID 33483472, 2021). "In ovarian cancer, it was found that RACGAP1 expression enhanced activation of RHOA and ERK proteins, and activation of its signaling induced cancer cell migration and invasion." (PMID 30866526, 2019). "In human ovarian cancer cells, JMS-053 impeded migration, disrupted spheroid growth, and decreased RhoA activity." (PMID 29492190, 2018). "For example, activated S1PR1 leads to the migration of ovarian cancer cells via PKC and RhoA signaling." (PMID 28831167, 2017). "A recent report that RhoA is up-regulated in ovarian cancer cells which express increased levels of TCTP, supports a possible role for RhoA-TCTP interaction in biological processes." (PMID 24918292, 2014). "In addition, we found that RhoA knockdown induced G1 arrest and apoptosis, decreased lamellipodia formation, and reduced cell migration and invasion, which indicates that RhoA downregulation may suppress the aggressive phenotypes of ovarian carcinoma cells." (PMID 24351810, 2013). "The association between RBP4 and tumor size suggests that RBP4 may promote tumor growth, as also described in ovarian cancer, where RBP4 enhances migration and proliferation by activating RhoA/Rock1 and ERK pathways and upregulating MMP2 and MMP9." (PMID 41007818, 2025). "Moreover, RhoA/Rock1 pathway activation and upregulation of CyclinD1 were involved in RBP4-induced ovarian cancer cell migration." (PMID 38913193, 2024). "The protein levels of RhoA did not change significantly in any of four types of ovarian cancer cells no matter in which PARD6A was overexpressed or silenced." (PMID 35379775, 2022). "An extensive literature search revealed that ESRP1 was also overexpressed in ovarian cancer tissues; therefore, we suggested that circ-NOLC1 could bind with ESRP1 and modulating CDK1 and RhoA expression." (PMID 33483472, 2021). "Additionally, RBP4, identified as a serum marker for ovarian cancer, directly induces cancer progression of ovarian cancer cells by increasing the expression of the cancer metastasis factors MM2 and MM9 through the RhoA/Rock1 pathway." (PMID 34068244, 2021). "Similar observations have been made in ovarian cancer, in which the synthetic glucocorticoid dexamethasone induced ROR1 expression, which correlated with elevated RHOA, YAP/TAZ, and BMI-1 levels in a panel of ovarian cancer cell lines as well as in the primary patient-derived cells." (PMID 33445713, 2021). "In addition, pitavastatin alters the subcellular localization of RhoA, CDC42 and Ras in several ovarian cancer cell lines." (PMID 32727400, 2020). "Whilst not yet demonstrated in ovarian cancer, RhoA is overexpressed in metastatic omental ovarian cancer deposits." (PMID 30909510, 2019). "Our result showed that, treatment of TOV-112D and TOV-1946 ovarian cancer cells with proteasome inhibitor MG-132 do not increase RhoA protein level compared with DMSO condition." (PMID 31209254, 2019). "Consequently, our study raises the possibility that CD151-α3β1 integrin complexes impact ovarian cancer malignancy largely by repressing the EMT-like process and potentially the RhoA activation from fibronectin-α5β1 integrin-mediated signaling." (PMID 25356755, 2014). "This could be due to the lack of effect on RhoA activity in ovarian cancer cells depleted of StarD13." (PMID 34958986, 2022).
ovarian carcinoma (continued). "Interestingly, treatment of ovarian cancer cells with L-citrulline in combination with HuArgI (Co)-PEG5000 rescued the cells from arginine deprivation-induced decrease in cell motility, cell adhesion and RhoA inactivation." (PMID 33423701, 2021). "Thus, we hypothesized that circ-NOLC1 might participate in ovarian cancer tumorigenesis and progression by binding the ESRP1, thus modulating RhoA and CDK1 expression." (PMID 33483472, 2021). "Thus, we hypothesized that circ-NOLC1 could promote ovarian cancer development by binding with miRNAs that inhibit the translation of CDK1 and RhoA." (PMID 33483472, 2021). "Indeed, in prior studies Zhang and Jiang described that RhoA inhibits the hypoxia-induced apoptosis in chondrocytes and Khaider and colleagues demonstrated that the inhibition of BID expression by Akt leads to resistance to TRAIL-induced apoptosis in ovarian cancer cells." (PMID 36113340, 2022).